CGAS (cyclic GMP-AMP synthase)
Diseases named in the same sentence as CGAS in open-access papers (continued):
Sharing a sentence is not in itself a finding about the gene and the disease.
acute pancreatitis (7 papers, 2022 to 2026). An acute inflammatory process that leads to necrosis of the pancreatic parenchyma. "The cGAS-STING pathway was found to be activated in acute pancreatitis and can induce cell injury by activating inflammation and by disturbing glucose and lipid metabolism." (PMID 36915161, 2023). "In fact, activation of cGAS–STING has been implicated in the promotion of inflammatory diseases, such as acute pancreatitis, acute kidney injury, and lung injury." (PMID 36289904, 2022).
age-related macular degeneration (7 papers, 2021 to 2026). Age-related loss of vision in the central portion of the retina (macula), secondary to retinal degeneration. "For example, dBET6 has been reported to play a therapeutic role in age-related macular degeneration by inhibiting the cGAS-STING pathway." (PMID 41585484, 2026). "In age-related macular degeneration (AMD), the release of mtDNA from the retinal pigment epithelium (RPE) mitochondria activates cGAS and drives noncanonical inflammasome activation, resulting in RPE degeneration." (PMID 35659309, 2022).
cardiomyopathy (7 papers, 2017 to 2025). A disease of the heart muscle or myocardium proper. "Despite these advances, the specific involvement of the cGAS/STING pathway in cardiomyopathy, as well as its underlying regulatory mechanisms, remains poorly understood." (PMID 40497954, 2025). "Over the past decades, various animal models have been developed to explore the pathophysiological mechanisms underlying cardiomyopathy, significantly advancing our understanding of the role played by the cGAS/STING signaling pathway in disease progression." (PMID 40497954, 2025). "Thus, cytosolic nDNA and mtDNA are increased and the DDR pathways are activated and pathogenic in a mouse model of DSP cardiomyopathy, whereas genetic blockade of CGAS is salubrious." (PMID 40608429, 2025). "To address this scientific gap, we first reviewed key findings on cGAS/STING signaling in various forms of cardiomyopathy, drawing from in vivo and in vitro studies, as well as clinical samples." (PMID 40497954, 2025). "Inflammation is a key factor in the development and progression of cardiomyopathy, and the cGAS/STING pathway has emerged as a significant contributor to this process." (PMID 40497954, 2025). "This review seeks to provide a comprehensive overview of molecular interventions targeting the cGAS/STING pathway in the context of cardiomyopathy." (PMID 40497954, 2025). "Collectively, these findings underscore the critical involvement of the cGAS/STING signaling pathway in the pathogenesis of sepsis-induced cardiomyopathy, highlighting its potential as a therapeutic target in septic cardiac dysfunction." (PMID 40497954, 2025). "Taken together, these findings underscore the therapeutic promise of targeting the cGAS/STING pathway in cardiomyopathy." (PMID 40497954, 2025). "A comprehensive literature review revealed that the cGAS/STING pathway is consistently activated in multiple forms of cardiomyopathy—including dilated (DCM) and hypertrophic cardiomyopathy (HCM)—when compared to non-failing (NF) control hearts." (PMID 40497954, 2025). "The cGAS-STING signaling is involved in various kinds of cardiomyopathy." (PMID 39664570, 2024). "We determined the activation and the role of the CDSP pathway, also known as the CGAS/STING1 pathway, in the pathogenesis of DSP cardiomyopathy." (PMID 40608429, 2025). "Recent evidence suggests that cGAS/STING-mediated inflammation and apoptosis are involved in myocardial injury and remodeling, potentially driving the development of cardiomyopathy." (PMID 40497954, 2025). "Another study examined the relationship between cGAS-STING and obesity-induced cardiomyopathy using HFD-fed db/db mice and H9C2 cells that were exposed to PA stimulation." (PMID 39664570, 2024). "To elucidate the critical role of cGAS/STING signaling in inflammation-mediated cardiomyopathies, we first systematically review the most important studies investigating this pathway across different cardiomyopathy subtypes." (PMID 40497954, 2025). "Targeting cGAS/STING may offer promising new strategies to reduce inflammation and improve outcomes in cardiomyopathy." (PMID 40497954, 2025). "In conclusion, cytosolic self-DNA (nDNA and mtDNA) is increased in cardiomyocytes in DSP cardiomyopathy and activates the CDSP (CGAS/STING1) pathway, which induces the expression of pro-inflammatory genes involved in cardiac dysfunction, cell death, and fibrosis." (PMID 40608429, 2025).
subarachnoid hemorrhage (7 papers, 2022 to 2024). A serious neurological disorder characterized by intracranial hemorrhage into the subarachnoid space. "Overall, the cGAS-cGAMP-STING signaling axis is closely associated with neuroinflammation after subarachnoid hemorrhage." (PMID 38169382, 2024). "The cGAS-cGAMP-STING signaling axis is closely associated with neuroinflammation after subarachnoid hemorrhage." (PMID 38169382, 2024). "In this study, we observed an increase in cGAS expression levels in rat brain tissue following subarachnoid hemorrhage (SAH)." (PMID 37770901, 2023). "We were the first to report that the cGAS selective inhibitor RU.521 ameliorates subarachnoid hemorrhage-induced brain injury via regulating microglial polarization and neuroinflammation mediated by the cGAS/STING/NF-κB pathway." (PMID 37770901, 2023). "Pharmacological inhibition of the cGAS-STING signaling pathway with RU.521 could potentially mitigate subarachnoid hemorrhage-induced brain injury by regulating microglial polarization and neuroinflammation." (PMID 37770901, 2023). "Based on the evidence presented, the hypothesis was that the cGAS-STING pathway could contribute to microglial polarization and neuroinflammation after experimental subarachnoid hemorrhage." (PMID 37770901, 2023).
Arthritis (6 papers, 2019 to 2024). Inflammation of a joint. "There is ample evidence demonstrating the dysregulation of the cGAS-STING signaling pathway implicated in the pathogenesis of various types of arthritis, especially OA and RA." (PMID 38765007, 2024). "Despite the distinct and multifactorial pathogeneses of OA and RA, substantial evidence suggests that the dysregulation of the cGAS-STING signaling pathway is implicated in the inflammatory pathogenesis of various types of arthritis, particularly in these two conditions." (PMID 38765007, 2024). "cGAS deficiency ameliorates symptoms in an arthritis model, suggesting that cGAS and STING may be involved in the development and progression of inflammatory arthritis." (PMID 38765007, 2024). "Understanding the intricate molecular signaling network of cGAS-STING in these arthritis forms offers potential avenues for targeted therapies." (PMID 38765007, 2024). "Arthritis-related indicators, such as inflammatory cell infiltration and joint swelling, are significantly ameliorated in the K/BxN arthritis model with cGAS-/- compared to the wild type." (PMID 37122709, 2023). "Irregularities in this pathway are linked to inflammatory diseases, prompting ongoing initiatives to devise therapeutic approaches targeting cGAS–STING for diverse conditions, especially arthritis." (PMID 38765007, 2024). "This review offers an up-to-date comprehension of the cGAS-STING pathway’s role in the development and therapeutic approaches for these arthritis types." (PMID 38765007, 2024). "The expression of cGAS has been reported to be upregulated in RA patients and CIA mice, and subcutaneous administration of NiH delayed the progression of RA and reduced the severity of arthritis in a CIA mouse model." (PMID 39450183, 2024). "After TNF treatment, cytoplasmic mtDNA binds to cGAS, and the absence of cGAS reduces interferon response, inflammatory cell infiltration, and joint swelling in the absence of an arthritis model mouse." (PMID 37492580, 2023). "Polyarthritis symptoms develop in DNaseII-/-Ifnar1-/- mice but did not appear in DNaseII-/-cGas-/- mice, suggesting that cGAS is important in DNA-induced arthritis pathology." (PMID 37354378, 2023).
colorectal tumors (6 papers, 2023 to 2026). "In colorectal tumors, cGAS deficiency impairs the intestinal epithelial barrier and exacerbates inflammation, leading to a more severe stage of tumor malignancy." (PMID 38782895, 2024). "Of note, cGAS deficiency significantly increased tumour burden, with greater numbers and larger sizes of colorectal tumours in cGAS-KO mice compared with their wild-type littermates." (PMID 39080411, 2024). "Above all, our data indicated that KIF18A inhibition stimulated type I IFN signaling and cGAS-STING activation in CIN+ colorectal tumors." (PMID 40175357, 2025). "Mechanically, KIF18A inhibition stimulated type I IFN signaling and cGAS-STING activation in CIN+ colorectal tumors." (PMID 40175357, 2025). "In our study, KIF18A inhibition by AM-1882 promoted cGAS-STING pathway activation in CIN+ colorectal tumors." (PMID 40175357, 2025). "Colorectal tumours developed in both cGAS+/+ and cGAS−/− mice after AOM/DSS treatment, predominantly in the distal colon." (PMID 39080411, 2024). "All cytosolic DNA-sensing and nuclease-related genes except cGAS, RNASEH2A, and RNASEH2B had decreased expression levels in colorectal tumor tissue compared to normal tissue." (PMID 39050748, 2024). "By using our IDTR approach, we showed for the first time that oncolytic adenovirus H101 could reactivate silenced cGAS, while silencing GAU1 long noncoding RNA (lncRNA) inhibited NF-κB p65 overactivation, resulting in efficient in vitro and in vivo antitumor efficacy in colorectal tumors." (PMID 38782895, 2024).
endometrial cancer (6 papers, 2022 to 2026). Primary or metastatic malignant neoplasm involving the endometrium (mucous membrane that lines the endometrial cavity). "In cancers like ovarian, cervical, and endometrial cancer, however, cGAS-STING is often suppressed, allowing tumor cells to evade immune detection." (PMID 39949780, 2025). "Therefore, activating the cGAS-STING pathway through POLE mutations may help improve the survival of patients with endometrial cancer, and the stimulation of intrinsic immunity in cancer cells by POLE mutations provides a theoretical basis for personalized treatment of malignant tumors." (PMID 39445027, 2024). "The activation of the cGAS-STING pathway by POLE mutation likely contributes to the advantageous survival of endometrial cancer patients with POLE mutations, as the cGAS-STING pathway has been associated with anti-tumor activity through the stimulation of inflammatory genes." (PMID 38238314, 2024). "It explores interactions between DNA damage response pathways and immune modulation, highlighting the impact of cGAS/STING activation or suppression in ovarian, cervical, and endometrial cancers." (PMID 39949780, 2025).
esophageal cancer (6 papers, 2022 to 2025). A primary or metastatic malignant neoplasm involving the esophagus. "cGAS has been implicated in the development and progression of esophageal cancer through a variety of mechanisms." (PMID 39050748, 2024). "We also examined the association between the expression of cGAS mRNA and the overall survival of HNSCC and esophageal cancer patients using the cBioPortal for Cancer Genomics." (PMID 35563740, 2022). "Lack of TFAM and its associated increase in cytoplasmic mitochondrial DNA led to increased cGAS-mediated autophagy and promotion of ESCC growth, shedding light on the interplay between mitochondrial dysfunction, cGAS, and autophagy in esophageal cancer." (PMID 39050748, 2024). "The expression of cGAS mRNA in HNSCC and esophageal cancer in tumor tissues was significantly higher than that in normal tissues." (PMID 35563740, 2022). "In esophageal carcinoma, the JAK2/STAT3 signaling pathway can promote cell cycle arrest and mitigate the cytotoxic effects induced by radiation, functioning as a downstream component of the cGAS-STING pathway." (PMID 39975558, 2025). "Kaplan–Meier analysis of the TCGA cohorts revealed that a high expression of cGAS was significantly correlated with a poor outcome for HNSCC patients, but not for esophageal cancer patients." (PMID 35563740, 2022).
fatty liver disease (6 papers, 2021 to 2025). A reversible condition wherein large vacuoles of triglyceride fat accumulate in liver cells via the process of steatosis. "Aerobic exercise has been shown to alleviate metabolic dysfunction-associated fatty liver disease by upregulating the adipokine Nrg4 and inhibiting hepatic cGAS–STING activation." (PMID 41008530, 2025). "Deletion of YAP in the Foxo1M-KO mice exacerbated HFD-induced hepatic steatosis, fibrosis, and inflammation and increased cGAS-STING-mediated innate immune responses." (PMID 39122845, 2024). "YAP directly interacts with the NICD, which is crucial for modulating its target gene Mb21d1 (cGAS) and downstream effector STING, leading to reduced liver steatosis and inflammation." (PMID 39122845, 2024).
Flavivirus Infections (6 papers, 2019 to 2023). Infections with viruses of the genus FLAVIVIRUS, family FLAVIVIRIDAE. "As a consequence, cGAS−/− mice are more susceptible to flavivirus infection." (PMID 37965539, 2023). "Mammalian cells mainly sense flavivirus infections through PRRs (including TLRs, RLRs and cGAS), and then their downstream signaling pathways are activated, ultimately inducing the production of IFN-I." (PMID 35154151, 2022). "Flavivirus infection induces the release of mitochondrial DNA, which is detected by cGAS, thereby activating the cGAS/STING pathway." (PMID 33925296, 2021). "Nevertheless, is mtDNA the only source of agonist inducing cGAS/STING response during Flavivirus infection?" (PMID 32899347, 2020). "In a typical flavivirus infection process, viral RNA could be identified by a variety of PRRs, such as TLRs, RLRs, cyclic GMP-AMP synthase (cGAS) and NLRs, which ultimately produce pro-inflammatory cytokines and induce antiviral status." (PMID 35154151, 2022). "Although there are a few publications on some of these DNA sensors and their proposed roles in controlling Flavivirus infection in different biological systems, there is yet to be any evidence of antagonism of these pathways by flaviviruses, other than the cGAS/STING pathway." (PMID 32899347, 2020). "In human cells, the host responds to flavivirus infection by recognizing viral nucleic acids through several distinct PRRs including RLRs, TLR-3, 7, and 8, NLRs, and the cyclic GMP-AMP synthase/stimulator of IFN genes- (cGAS-STING-) dependent sensing pathway." (PMID 32455136, 2020). "The cGAS-STING pathway, which is known to sense DNA viruses, has also been recently involved in restricting flavivirus infections." (PMID 32455136, 2020). "Besides the RNA sensors TLR3, RIG-I, and MDA5, the cGAS-STING axis, triggered by the presence of DNA in the cytoplasm, has also been shown to be involved in flavivirus infections." (PMID 37965539, 2023). "Given that the cGAS-STING axis also effectively restricts flavivirus infection, it is not surprising that these viruses have mechanisms to evade this pathway." (PMID 31652496, 2019).
idiopathic pulmonary fibrosis (6 papers, 2023 to 2025). Idiopathic pulmonary fibrosis (IPF) is a nonneoplastic pulmonary disease that is characterized by the formation of scar tissue within the lungs in the absence of any known cause. "In epithelial cells, particularly alveolar epithelial cells (AECs), the activation of the cGAS-STING pathway is considered the initiating and central mechanism in the pathogenesis of idiopathic pulmonary fibrosis (IPF)." (PMID 41226461, 2025).
intervertebral disc degeneration (6 papers, 2021 to 2025). "Mitophagy alleviates intervertebral disc degeneration (IVDD) by suppressing cGAS–STING and NLRP3 inflammasome-mediated pyroptosis pathways; however, its metabolic regulatory mechanism remains unexplored." (PMID 41199783, 2025). "It has been reported that NLRP3 inflammasome activation was modulated by the cGAS‐STING pathway in some diseases including intervertebral disc degeneration and acute liver injury." (PMID 40522023, 2025). "The levels of cGAS, STING, and NLRP3 were significantly upregulated in intervertebral disc degeneration (IDD) patients, and epigallocatechin gallate (EGCG) treatment could inhibit cell apoptosis by target cGAS/STING/NLRP3." (PMID 40303074, 2024).
kidney injury (6 papers, 2022 to 2025). Trauma to the kidney. "We believe that studying the role of cGAS/STING signaling pathway in cisplatin induced AKI can provide a basis for prevention and treatment of kidney injury." (PMID 41497308, 2025).
latent infection (6 papers, 2016 to 2024). "The cleavage of a DENV protease-sensitive STING can be further enhanced by coculture with neighboring cells producing 2′3′-cGAMP, either by DNA transfection of cGAS or by reactivating Epstein–Barr virus from latent infection." (PMID 32576686, 2020). "We also observed similar findings and in addition, demonstrate the interactions of cGAS with H2B, IFI16, BRCA1, and STING in the cytoplasm of cells during de novo infection as well as in latent infection." (PMID 27764250, 2016). "As the cGAS-MITA-TBK1 axis plays an indispensable role in host defense against DNA viruses infection, the DNA viruses have developed numerous means to counteract this signaling pathway for replication and latent infection." (PMID 34745071, 2021). "As the cGAS-MITA-TBK1 axis plays a crucial role in host defense against DNA viruses, the DNA viruses have evolved various mechanisms to antagonize this signaling pathway for replication and latent infection." (PMID 31107917, 2019). "Nevertheless, these findings suggest that IFI16, H2B, BRCA1, cGAS and STING associate in the cytoplasm during KSHV de novo and latent infection that is independent of ASC." (PMID 27764250, 2016).
metabolic syndrome (6 papers, 2021 to 2025). A cluster of metabolic risk factors for CARDIOVASCULAR DISEASES and TYPE 2 DIABETES MELLITUS. "Thus, herein, we constructed a mRNAs (DDX58, NFκB1& CHUK)—(miR-1976) panel linked to metabolic syndrome and pancreatic cell dysfunction as well as be enrolled in the cGAS-STING pathway via in silico data analysis." (PMID 36915161, 2023). "cGAS-STING pathway is a vital natural sensor of host immunity that can defend various tissues and organs against pathogenic infection, metabolic syndrome, cellular stress and cancer metastasis." (PMID 34386500, 2021). "For instance, targeting FAs might enhance cGAS‐promoted antiviral and antitumor immune surveillance, particularly in patients with metabolic syndromes." (PMID 36950761, 2023). "HFDs and metabolic syndromes attenuate immunity and increase the morbidity and mortality rates of infections.[8a,b] To evaluate the role of FA in the cGAS‐mediated anti‐infection immunity, we treated cGAS wild type (WT) and knockout (KO) mice with OA injection and/or HSV infection." (PMID 36950761, 2023).
metastatic disease (6 papers, 2022 to 2025). "We further employed Iimmunohistochemical staining was employed to examine immune system activation and detect the production of interferon beta (IFN‐β) in lung metastatic tumors of NOD‐SCID mice after drug treatment, as IFN‐β is a downstream product activated following cGAS‐STING activation." (PMID 39739317, 2025). "Fifty-nine tumor samples from patients with pathologically confirmed squamous cell carcinoma of the larynx, stage I–IV non-metastatic disease, who were treated at the University Hospital of Split, were immunohistochemically stained for the expression of STING, cGAS, CD8, CD68, and CD163." (PMID 37444620, 2023). "Consequently, the activated caspase-3–GSDME and cGAS–STING pathways boost the immune response, significantly inhibiting the primary and distant metastatic tumors." (PMID 37342347, 2023).